SERINC3 (serine incorporator 3)
Description:
Restriction factor required to restrict infectivity of lentiviruses, such as HIV-1: acts by inhibiting an early step of viral infection. Impairs the penetration of the viral particle into the cytoplasm. Non-ATP-dependent, non-specific lipid transporter for phosphatidylserine, phosphatidylcholine, and phosphatidylethanolamine. Functions as a scramblase that flips lipids in both directions across the membrane. Phospholipid scrambling results in HIV-1 surface exposure of phosphatidylserine and loss of membrane asymmetry, which leads to changes in HIV-1 Env conformation and loss of infectivity.
Synonyms: DIFF33; TDE1; SBBI99; TDE; TMS-1; AIGP1
Tractability: Antibody: UniProt places it where antibodies can reach, with high confidence; its Gene Ontology location is reachable by antibodies, with high confidence; UniProt predicts a signal peptide or a membrane-spanning region. PROTAC: ubiquitination databases record sites on it; its protein half-life has been measured.
Gene: Protein-coding gene on chromosome 20 (44,496,221 to 44,522,094, reverse strand). Ensembl gene ENSG00000132824.
Subcellular location: Cell membrane; Golgi apparatus membrane; Cytoplasm, perinuclear region
Pathways (Reactome):
Metabolism: Serine metabolism
Gene Ontology:
Molecular function: molecular carrier activity; phospholipid scramblase activity; protein binding
Biological process: antiviral innate immune response; plasma membrane phospholipid scrambling
Cellular component: plasma membrane; Golgi membrane; membrane; Golgi apparatus; perinuclear region of cytoplasm
Genetic constraint (gnomAD): Loss-of-function variants: 19 observed, 44.06 expected, observed/expected ratio (o/e) 0.43, 90% interval 0.3 to 0.63. The upper end of that interval is the gene's LOEUF score, 0.63, which puts it in group 2 of 6, group 1 being the genes least tolerant of losing a copy. Missense variants: 527 observed, 551.04 expected, observed/expected ratio (o/e) 0.96, 90% interval 0.89 to 1.03. Synonymous variants: 211 observed, 204.52 expected, observed/expected ratio (o/e) 1.03, 90% interval 0.92 to 1.16.
Homologues: Orthologues: chimpanzee SERINC3 (99% identical), macaque SERINC3 (99% identical), dog SERINC3 (85% identical), rabbit SERINC3 (84% identical), pig SERINC3 (83% identical), mouse Serinc3 (78% identical), rat Serinc3 (78% identical), guinea pig SERINC3 (73% identical), tropical clawed frog serinc3 (66% identical), Drosophila melanogaster Serinc (41% identical), Caenorhabditis elegans Y57E12AL.1 (38% identical), Caenorhabditis elegans R11H6.2 (38% identical), and 2 more. Paralogues in human: SERINC1 (59% identical), SERINC2 (48% identical), SERINC5 (38% identical), SERINC4 (32% identical).
Diseases named in the same sentence as SERINC3 in open-access papers:
SERINC3 is named in the same sentence as 19 diseases in open-access papers, as found by Europe PMC text mining. Sharing a sentence is not in itself a finding about the gene and the disease. The quoted sentences say what the papers report.
prostate carcinoma (3 papers, 2013 to 2023). A carcinoma that arises from epithelial cells of the prostate gland. "Functional studies on CSAD and SERINC3 genes and their regulators are needed to further delineate their roles in prostate cancer, which would reveal their potential for further interventions." (PMID 36831650, 2023). "By using a machine learning approach, we found that the expression of the genes CSAD and SERINC3 discriminates between better and worse prognosis (low and high risk) for progression-free survival (PFS) of prostate cancer patients when they are stratified according to the Gleason score." (PMID 36831650, 2023). "However, EPB41L5 and SERINC3 had a high rank based on mutational burden and CNVs, ELOVL6 was annotated as an oncogene in prostate cancer, and PPM1H has been proposed to be an oncogene, due to its relation to PPM1D (a well-studied oncogene in breast, ovarian, and brain cancers)." (PMID 32605588, 2020). "For the genes that we show are involved in prostate cancer prognosis (see further section), CSAD had increased expression in prostate cancer (fold-change = 1.61, FDR < 0.001), while the expression of SERINC3 did not change according to the criteria used." (PMID 36831650, 2023).
viral infection (2 papers, 2020 to 2022). "In a previous EPF genome-wide expression study (GWES), several genes involved in the early stages of viral infection were overexpressed in patients with the generalized form of EPF compared to healthy individuals, including IFITM3, APOBEC3A, APOBEC3G, OAS1, OASL, SERINC3, and RPLP2." (PMID 35632621, 2022).
gastric cancer (1 paper, 2020). A primary or metastatic malignant neoplasm involving the stomach. "To further explore the microarray data, we evaluated the transcriptional levels of TIPRL, SERINC3, COPS6, and SELM in 40 frozen gastric tissues of gastric cancer patients by real-time PCR." (PMID 32719745, 2020).
HIV-1 infection (1 paper, 2022). The type species of lentivirus and the etiologic agent of acquired immunodeficiency syndrome (AIDS). "The results showed that mRNA levels of already known host restriction factors which inhibit HIV-1 infection, TRIM5α, MX2, SAMHD1, SERINC3, SERINC5, IFITM2, IFITM3, ApoE, and PSGL-1 were not significantly elevated by γ-IFN." (PMID 35883685, 2022).
hyperlipidaemia (1 paper, 2025). "Our results also suggest that hyperlipidaemia contributes to alteration in early immature cDC1 and in the abundance of late immature cDC1 cells, which was associated with dramatic change in gene expression of Tnfaip3, Serinc3, Apol7c, and Tifab." (PMID 40934103, 2025).
infection (5 papers, 2021 to 2025). The state of being infected such as from the introduction of a foreign agent such as serum, vaccine, antigenic substance or organism. "According to an analysis of expression of quantitative trait loci (eQTLs) of 60 virus restriction factors, genetic control of the expression of SERINC3 may underlie inter-individual differences in risk or severity of infection with SARS-COV-2." (PMID 35433679, 2022). "The lower ability of the R178G mutation to counteract SERINC3 and -5 may indicate that, during the course of infection, the selective pressure of this restriction protein is lost in these individuals, explaining the selective outgrowth of HIV-1 variants containing the R178G mutation in Nef." (PMID 33800773, 2021). "SERINC3/5 were initially identified as cell restriction factors that can potently suppress HIV-1 infectivity by incorporating into budding viral particles and impairing subsequent virion fusion and infection of new target cells." (PMID 39292108, 2024). "Interestingly, a new study demonstrated that SERINC3 and SERINC5 promote innate immune signaling, resulting in increased production of type I IFNs and pro-inflammatory cytokines, thereby inhibiting the infection of HIV-1, vesicular stomatitis virus (VSV), and Zika virus (ZIKV)." (PMID 35433679, 2022).
tumor (1 paper, 2020). "The downregulated expression of IL-1, CTSW, NR1H3 and CCR8 (with HR < 1) indicated these molecules as tumor suppressors, whereas the upregulated expression levels of LY86, RABGEF1, CYFIP2 and SERINC3 (with HR > 1) indicated these molecules as oncogenes." (PMID 33816214, 2020).
SERINC3 also shares sentences with these, for which no sentence is quoted: AIDS (1 paper); Astrocytoma (1); brain cancer (1); breast carcinoma (1); breast tumors (1); cancer (1); diffuse large B-cell lymphoma (1); inflammatory bowel disease (1); melanoma (1); testicular germ cell tumor (1); thyroid carcinoma (1); uterine carcinosarcoma (1).